H2BC21 (H2B clustered histone 21)
Description:
Core component of nucleosome. Nucleosomes wrap and compact DNA into chromatin, limiting DNA accessibility to the cellular machineries which require DNA as a template. Histones thereby play a central role in transcription regulation, DNA repair, DNA replication and chromosomal stability. DNA accessibility is regulated via a complex set of post-translational modifications of histones, also called histone code, and nucleosome remodeling. Has broad antibacterial activity. May contribute to the formation of the functional antimicrobial barrier of the colonic epithelium, and to the bactericidal activity of amniotic fluid.
Synonyms: H2B/q; H2BFQ; HIST2H2BE; H2B.1; H2BE; H2B-GL105; GL105; H2B; H2BGL105; H2BQ
Tractability: PROTAC: UniProt records ubiquitination sites on it; ubiquitination databases record sites on it.
Gene: Protein-coding gene on chromosome 1 (149,884,459 to 149,886,682, reverse strand). Ensembl gene ENSG00000184678.
Subcellular location: Nucleus; Chromosome
Subcellular location (Human Protein Atlas): Nucleoplasm; Cytosol
Pathways (Reactome):
Gene expression (Transcription): B-WICH complex positively regulates rRNA expression; DNA methylation; ERCC6 (CSB) and EHMT2 (G9a) positively regulate rRNA expression; MLL4 and MLL3 complexes regulate expression of PPARG target genes in adipogenesis and hepatic steatosis; NoRC negatively regulates rRNA expression; PRC2 methylates histones and DNA; RNA Polymerase I Promoter Escape; RNA Polymerase I Promoter Opening; RUNX1 regulates genes involved in megakaryocyte differentiation and platelet function; RUNX1 regulates transcription of genes involved in differentiation of HSCs; Regulation of endogenous retroelements by KRAB-ZFP proteins; Regulation of endogenous retroelements by Piwi-interacting RNAs (piRNAs); Regulation of endogenous retroelements by the Human Silencing Hub (HUSH) complex; SIRT1 negatively regulates rRNA expression; Transcriptional regulation by small RNAs
Chromatin organization: CHD1 and CHD2 subfamily; CHD6, CHD7, CHD8, CHD9 subfamily; ChAHP complex assembly; HATs acetylate histones; HDACs deacetylate histones; Interaction of NuRD complexes with transcription factors; NuRD complex assembly
DNA Repair: Cleavage of the damaged purine; Cleavage of the damaged pyrimidine; Nonhomologous End-Joining (NHEJ); Processing of DNA double-strand break ends; Recognition and association of DNA glycosylase with site containing an affected purine; Recognition and association of DNA glycosylase with site containing an affected pyrimidine; Recruitment and ATM-mediated phosphorylation of repair and signaling proteins at DNA double strand breaks
Cell Cycle: Condensation of Prophase Chromosomes; Deposition of new CENPA-containing nucleosomes at the centromere; G2/M DNA damage checkpoint; Inhibition of DNA recombination at telomere; Packaging Of Telomere Ends
Developmental Biology: Activation of anterior HOX genes in hindbrain development during early embryogenesis; Chromatin modifications during the maternal to zygotic transition (MZT); Replacement of protamines by nucleosomes in the male pronucleus; Transcriptional regulation of granulopoiesis
Disease: Defective pyroptosis; Dengue Virus-Host Interactions
and 17 more pathways
Gene Ontology:
Molecular function: protein binding; DNA binding; structural constituent of chromatin; protein heterodimerization activity
Biological process: antibacterial humoral response; antimicrobial humoral immune response mediated by antimicrobial peptide; defense response to Gram-positive bacterium; innate immune response in mucosa; chromatin organization; nucleosome assembly
Cellular component: extracellular exosome; extracellular region; nucleus; nucleoplasm; nucleosome; chromosome
Genetic constraint (gnomAD): Loss-of-function variants: 2 observed, 6.14 expected, observed/expected ratio (o/e) 0.33, 90% interval 0.13 to 1.02. That is too few expected variants to judge how well the gene tolerates losing a copy. Missense variants: 98 observed, 175.5 expected, observed/expected ratio (o/e) 0.56, 90% interval 0.47 to 0.66. Synonymous variants: 109 observed, 75.28 expected, observed/expected ratio (o/e) 1.45, 90% interval 1.24 to 1.7.
Homologues: Orthologues: dog H2BC21 (100% identical), rabbit H2BC21 (100% identical). Paralogues in human: H2BC10 (99% identical), H2BC11 (99% identical), H2BC17 (99% identical), H2BC4 (99% identical), H2BC6 (99% identical), H2BC7 (99% identical), H2BC8 (99% identical), H2BC12 (98% identical), H2BC15 (98% identical), H2BC3 (98% identical), H2BC5 (98% identical), H2BC9 (98% identical), and 9 more.
Diseases named in the same sentence as H2BC21 in open-access papers:
H2BC21 is named in the same sentence as 122 diseases in open-access papers, as found by Europe PMC text mining. Sharing a sentence is not in itself a finding about the gene and the disease. The quoted sentences say what the papers report.
glioma (12 papers, 2014 to 2025). A benign or malignant brain and spinal cord tumor that arises from glial cells (astrocytes, oligodendrocytes, ependymal cells). "Univariate and multivariate Cox analysis showed that H2BC5, H2BC9, H2BC11, and H2BC21 are high-risk factors for glioma." (PMID 36387186, 2022). "In particular, high H2BC5, H2BC9, H2BC11, and H2BC21 expression was associated with poor glioma prognosis." (PMID 36387186, 2022). "H2BC21 has also been linked to poor prognosis in gliomas and is associated with tumor immunity." (PMID 40362252, 2025). "Enrichment analysis of H2BC5, H2BC9, H2BC11, and H2BC21 was also conducted to understand how the H2B gene is involved in the pathological progression of glioma." (PMID 36387186, 2022). "The methylation status of H2BC5, H2BC9, H2BC11, and H2BC21 in different glioma cohorts was evaluated in the Methsurv database." (PMID 36387186, 2022). "Expression of H2BC5, H2BC9, H2BC11, and H2BC21 was higher in glioma tissues." (PMID 36387186, 2022). "In summary, H2BC5, H2BC9, H2BC11, and H2BC21 were independent prognostic indicators of glioma, and H2BC9 and H2BC11 may correlate with tumor immunity." (PMID 36387186, 2022). "Collectively, these data indicated that H2BC5, H2BC9, H2BC11, and H2BC21 could independently predict glioma prognosis." (PMID 36387186, 2022). "Kaplan-Meier survival analysis showed that high expression of H2BC5, H2BC9, H2BC11, and H2BC21 correlated with a poor OS, DFS, and PFI of glioma patients." (PMID 36387186, 2022). "Moreover, the ROC curve showed that H2BC5, H2BC9, H2BC11, and H2BC21 all had meaningful predictive power for glioma, especially H2BC9 and H2BC11, which showed excellent sensitivity and specificity in predicting the survival of glioma patients, with an area under the curve (AUC) of >0.8." (PMID 36387186, 2022).
cervical cancer (5 papers, 2014 to 2025). A primary or metastatic malignant neoplasm involving the cervix. "Using genetic variants as instrumental variables, we identified key genes such as FUOM, H2BC21, LAMTOR4, and PRKCQ, which demonstrated direct effects on cervical cancer susceptibility." (PMID 40817807, 2025). "The correlation of FUOM and H2BC21 with immunosuppressive M2 macrophages and anti‐tumor immune cells further underscores their dual role in regulating the TME, providing actionable targets for reprogramming immune responses in cervical cancer." (PMID 40817807, 2025). "Additionally, PRKCQ and H2BC21 were significantly overexpressed in HeLa cells, whereas LAMTOR4 showed a slight but statistically significant decrease (p < 0.01), suggesting differential roles for these genes in cervical cancer biology." (PMID 40817807, 2025).
astrocytoma (1 paper, 2022). "The GSE4271 and GSE4412 datasets were used as a supplement to the results and suggested the prognostic value of H2BC5, H2BC9, H2BC21 on astrocytoma." (PMID 36387186, 2022).
tumor (78 papers, 2011 to 2025). "For example, FUOM was strongly implicated in Th17 cell differentiation, a pathway known to drive tumor‐promoting inflammation, while H2BC21 was associated with TNF and IL‐17 signaling, which are integral to immune evasion and chronic inflammation in cancer." (PMID 40817807, 2025). "Genes such as H2BC21 were enriched in DNA repair pathways, highlighting their potential as therapeutic targets for sensitizing tumor cells to DNA‐damaging treatments such as chemotherapy and radiotherapy." (PMID 40817807, 2025). "Genes such as FUOM and H2BC21 were positively correlated with immunosuppressive M2 macrophages and activated CD4 memory T cells, while negatively correlated with anti‐tumor immune cells such as resting CD4 memory T cells and activated dendritic cells." (PMID 40817807, 2025). "The model includes PRKCQ, FUOM, H2BC21, LAMTOR4, and HCG22, along with critical clinical factors such as age, tumor grade, and tumor stage (T and N)." (PMID 40817807, 2025). "Key findings include the identification of FUOM, PRKCQ, H2BC21, and LAMTOR4 as pivotal regulators of tumor progression and immune modulation, with FUOM playing a particularly prominent role in promoting cell proliferation, migration, and colony formation, as demonstrated by experimental validation." (PMID 40817807, 2025). "The analysis of H2B family gene expression in glioma showed that H2BC5, H2BC9, H2BC11, and H2BC21 can be used as independent predictive factors for glioma prognosis, and overexpression of H2BC9 and H2BC11 may lead to tumor deterioration through the immune system." (PMID 36387186, 2022).
H2BC21 also shares sentences with these, for which no sentence is quoted: cancer (66 papers); infection (38); breast cancer (26); melanoma (13); lupus (12); osteosarcoma (10); lung carcinoma (8); viral infection (8); pancreatic cancer (6); glioblastoma (5); alcoholism (4); autoimmune disease (4); bladder cancer (4); colorectal cancer (4); leukemia (4); adenocarcinoma (3); gastric cancer (3); lung adenocarcinoma (3); ovarian carcinoma (3); prostate carcinoma (3); Sepsis (3); acute lymphoblastic leukemia (2); Autoimmunity (2); blood cancer (2); brain tumor (2); cholangiocarcinoma (2); cyst (2); diabetes (2); diabetic nephropathy (2); esophageal carcinoma (2).
A further 88 diseases each share a sentence with H2BC21 in 2 papers or fewer.